CGB2 (chorionic gonadotropin subunit beta 2)
Tractability: Antibody: UniProt places it where antibodies can reach, with medium confidence; UniProt predicts a signal peptide or a membrane-spanning region; its Gene Ontology location is reachable by antibodies, with medium confidence.
Gene: Protein-coding gene on chromosome 19 (49,031,890 to 49,033,238, forward strand). Ensembl gene ENSG00000104818.
Subcellular location: Secreted
Gene Ontology:
Molecular function: hormone activity
Biological process: G protein-coupled receptor signaling pathway; cell communication; signaling
Cellular component: extracellular region
Genetic constraint (gnomAD): Loss-of-function variants: 4 observed, 4.74 expected, observed/expected ratio (o/e) 0.84, 90% interval 0.41 to 1.73. That is too few expected variants to judge how well the gene tolerates losing a copy. Missense variants: 66 observed, 97.85 expected, observed/expected ratio (o/e) 0.67, 90% interval 0.55 to 0.83. Synonymous variants: 30 observed, 41.92 expected, observed/expected ratio (o/e) 0.72, 90% interval 0.53 to 0.97.
Homologues: Orthologues: macaque CGB8 (82% identical), Drosophila melanogaster Gpb5 (15% identical). Paralogues in human: CGB3 (98% identical), CGB5 (98% identical), CGB8 (98% identical), CGB7 (98% identical), CGB1 (94% identical), LHB (69% identical), TSHB (30% identical), FSHB (25% identical), GPHB5 (21% identical).
Diseases named in the same sentence as CGB2 in open-access papers:
CGB2 is named in the same sentence as 16 diseases in open-access papers, as found by Europe PMC text mining. Sharing a sentence is not in itself a finding about the gene and the disease. The quoted sentences say what the papers report.
ovarian carcinoma (2 papers, 2013 to 2019). A malignant neoplasm originating from the surface ovarian epithelium. "Presence of mRNA arising from CGB1 and CGB2 genes appears to be a unique feature of a subset of ovarian cancers." (PMID 31362717, 2019). "CGB1 and CGB2 genes were detected to be transcriptionally active only in 20% of tested ovarian cancer tissues and at the lowest level across all tested CGB genes of the cluster." (PMID 31362717, 2019). "Guided by this information, we decided to analyse the activity of CGB1 and CGB2 in ovarian cancer tissues in order to compare their expression pattern with normal ovaries lacking cancerous changes and CG-producing placentas." (PMID 23774837, 2013). "Furthermore presence of mRNA arising from CGB1 and CGB2 genes appears to be a unique feature of a subset of ovarian cancers." (PMID 31362717, 2019). "In fact we previously demonstrated the presence of CGB1 and CGB2 transcripts in ovarian carcinomas." (PMID 31362717, 2019). "Notably transcription of CGB1 and CGB2 was detected in 20% of ovarian cancer samples." (PMID 31362717, 2019).
bladder cancer (1 paper, 2020). "CGB1 and CGB2 expression has also been confirmed in breast and bladder cancer cell lines, as well as in ovarian cancer tissue." (PMID 32957442, 2020). "Indeed, it was reported that in bladder cancer cell lines, it is CGB2 expression, but not other CGB genes, which correlates with the amount of functional free hCGβ protein secreted by cancer cells and with cancer growth." (PMID 32957442, 2020).
ovarian tumours (1 paper, 2019). "In the case of CGB1 and CGB2 gene transcripts, RT-qPCR assay showed that more than 20% of analyzed ovarian tumours expressed CGB1–2, but none of the control ovarian tissues contained detectable levels of these genes transcripts." (PMID 31362717, 2019).
cancer (1 paper, 2020). A tumor composed of atypical neoplastic, often pleomorphic cells that invade other tissues. "Since the transcriptional activity of CGB1 and CGB2 in cancer was mainly shown in cell lines, the aim of the present study was to demonstrate the expression of these genes in human cancer tissues of different origin." (PMID 32957442, 2020). "In order to verify the transcriptional activity of CGB1 and CGB2 genes in cancer, we analyzed data collected in TCGA." (PMID 32957442, 2020). "It was also demonstrated that specific targeting of CGB1 and CGB2 with siRNA was much more effective in reducing cancer cell numbers than silencing other CGB genes." (PMID 32957442, 2020). "First, the screening of TCGA transcriptome data related to CGB1 and CGB2 gene expression in different cancers was performed." (PMID 32957442, 2020). "In the same manner, CGB1 and CGB2 may promote the pregnancy-like invasion of cancer cells into specific microenvironments, and later tumor growth and metastasis." (PMID 32957442, 2020). "Despite the fact that the studied genes’ expression levels in cancer tissues were low, with the median often equaling zero, the transcriptional activity of the CGB1 and CGB2 genes in cancerous tissues of different origin was confirmed." (PMID 32957442, 2020).
tumor (1 paper, 2020). "Further studies are needed in order to verify the hypothesis that CGB1 and CGB2 genes are involved in tumor growth, invasion and metastasis." (PMID 32957442, 2020). "Significant differences in CGB2 expression in non-malignant tissues and primary tumor samples were noted for BLCA, ESCA, HNSC, LUSC and UCEC; p-value: 1 × 10−6, 0.006, <1 × 10−12, <1 × 10−12, 0.0017 respectively." (PMID 32957442, 2020).
CGB2 also shares sentences with these, for which no sentence is quoted: bladder urothelial carcinoma (1 paper); cervical squamous cell carcinoma (1); esophageal carcinoma (1); head and neck squamous cell carcinoma (1); lung squamous cell carcinoma (1); ovarian serous cystadenocarcinoma (1); pancreatic adenocarcinoma (1); testis germ cell tumors (1); thymoma (1); uterine carcinosarcoma (1); uterine corpus endometrial carcinoma (1).